DYRK2 (dual specificity tyrosine phosphorylation regulated kinase 2)
Description:
Serine/threonine-protein kinase involved in the regulation of the mitotic cell cycle, cell proliferation, apoptosis, organization of the cytoskeleton and neurite outgrowth. Can phosphorylate histone H1, histone H3 and histone H2B (in vitro). Can phosphorylate CARHSP1 (in vitro). Functions in part via its role in ubiquitin-dependent proteasomal protein degradation. Phosphorylates NFATC1, and thereby inhibits its accumulation in the nucleus and its transcription factor activity. May play a general role in the priming of GSK3 substrates. Phosphorylates EIF2B5 at 'Ser-544', enabling its subsequent phosphorylation and inhibition by GSK3B. Likewise, phosphorylation of NFATC1, CRMP2/DPYSL2 and CRMP4/DPYSL3 promotes their subsequent phosphorylation by GSK3B. Inactivates GYS1 by phosphorylation at 'Ser-641', and potentially also a second phosphorylation site, thus regulating glycogen synthesis. Mediates EDVP E3 ligase complex formation and is required for the phosphorylation and subsequent degradation of KATNA1. Phosphorylates TERT at 'Ser-457', promoting TERT ubiquitination by the EDVP complex. Phosphorylates SIAH2, and thereby increases its ubiquitin ligase activity. Promotes the proteasomal degradation of MYC and JUN, and thereby regulates progress through the mitotic cell cycle and cell proliferation. Acts as a positive regulator of smoothened signaling by mediating phosphorylation of GLI2 and GLI3 in response to smoothened activation, promoting their dissociation from SUFU inhibitor and translocation to the nucleus. Can also acts as a negative regulator of smoothened by catalyzing phosphorylation of GLI2 and GLI3 and promote their proteasomal degradation. Plays a role in cytoskeleton organization and neurite outgrowth via its phosphorylation of DCX and DPYSL2 (By similarity).
Tractability: Small molecule: a structure with a bound ligand is known; a high-quality ligand is known; it has a binding pocket of medium quality; it belongs to a druggable protein family. PROTAC: UniProt records ubiquitination sites on it; its protein half-life has been measured; a small molecule that binds it is known.
Target class: Enzyme; Protein Kinase; Kinase; CMGC protein kinase DYRK family; CMGC protein kinase group; CMGC protein kinase Dyrk2 subfamily
Chemical probes: MU1210 (high quality)
Gene: Protein-coding gene on chromosome 12 (67,647,913 to 67,665,406, forward strand). Ensembl gene ENSG00000127334.
Subcellular location: Cytoplasm; Nucleus
Subcellular location (Human Protein Atlas): Nucleoplasm; Cytosol
Gene Ontology:
Molecular function: ATP binding; magnesium ion binding; manganese ion binding; protein binding; protein serine/threonine kinase activity; protein tyrosine kinase activity; protein kinase activity; protein serine kinase activity; protein serine/threonine/tyrosine kinase activity
Biological process: DNA damage response; negative regulation of calcineurin-NFAT signaling cascade; positive regulation of glycogen biosynthetic process; positive regulation of smoothened signaling pathway; protein phosphorylation; smoothened signaling pathway
Cellular component: cytoplasm; cytosol; nucleoplasm; nucleus; ubiquitin ligase complex; cytoskeleton; protein-containing complex; ribonucleoprotein complex
Genetic constraint (gnomAD): Loss-of-function variants: 12 observed, 39.36 expected, observed/expected ratio (o/e) 0.3, 90% interval 0.19 to 0.49. The upper end of that interval is the gene's LOEUF score, 0.49, which puts it in group 2 of 6, group 1 being the genes least tolerant of losing a copy. Missense variants: 678 observed, 787.21 expected, observed/expected ratio (o/e) 0.86, 90% interval 0.81 to 0.92. Synonymous variants: 322 observed, 308.46 expected, observed/expected ratio (o/e) 1.04, 90% interval 0.95 to 1.14.
Homologues: Orthologues: chimpanzee DYRK2 (100% identical), macaque DYRK2 (99% identical), pig DYRK2 (99% identical), dog DYRK2 (99% identical), guinea pig DYRK2 (99% identical), mouse Dyrk2 (97% identical), rat Dyrk2 (96% identical), rabbit DYRK2 (89% identical), tropical clawed frog dyrk2 (86% identical), zebrafish dyrk2 (84% identical), Caenorhabditis elegans C16A11.10 (14% identical), Caenorhabditis elegans Y111B2A.1 (14% identical). Paralogues in human: DYRK3 (59% identical), DYRK4 (40% identical), HIPK2 (28% identical), DYRK1A (27% identical), HIPK1 (27% identical), HIPK3 (26% identical), DYRK1B (25% identical), CLK1 (21% identical), CLK3 (20% identical), CLK4 (20% identical), HIPK4 (19% identical), CLK2 (18% identical).
Diseases named in the same sentence as DYRK2 in open-access papers:
DYRK2 is named in the same sentence as 94 diseases in open-access papers, as found by Europe PMC text mining. Sharing a sentence is not in itself a finding about the gene and the disease. The quoted sentences say what the papers report.
breast carcinoma (16 papers, 2016 to 2025). "According to the COSMIC database, DYRK2 mutations have been identified in human breast cancer through the genome-wide analysis of various cancers." (PMID 37886981, 2023). "Additional evidence for the involvement of DYRK2 in cancers came from a germline-somatic association study of genetic alterations in multiple cohorts of breast cancer patients." (PMID 32751160, 2020). "Repression of DYRK2 expression has been associated with the progression of cancers such as hepatocellular carcinoma, gastric cancer, colorectal cancer, and breast cancer, and we studied this association in CML14,78–81." (PMID 33067577, 2020). "Complementing this information, a recent study with 715 samples of patients with breast cancer have shown that high protein levels of nuclear DYRK2 were associated with significantly reduced cancer survival and a shorter time to recurrence specifically within the TNBC subtype cohort." (PMID 33376136, 2021). "To date, the most controversial role for DYRK2 associated with tumors is in breast cancer." (PMID 32751160, 2020). "For instance, DYRK2’s regulatory roles in cell survival, differentiation, and apoptosis are tissue-dependent, affecting breast cancer differently than other cancers." (PMID 40190550, 2025). "The role of DYRK2 in breast cancer has been investigated in tissue samples, cell lines, and xenograft mouse models." (PMID 37886981, 2023). "Some studies have reported that DYRK2 is a tumor suppressor in many cancer types, whereas others have reported that it is an oncogene in lung, esophageal, ovarian, prostate, and breast cancers." (PMID 37886981, 2023). "Multiple studies looking at the role of DYRK2 in breast cancer have used the hormone receptor–positive and HER2-negative MCF7 cell line for xenograft studies." (PMID 33376136, 2021). "Comparative tumor growth in the DYRK2 null versus parental GEMM over different subtypes would be a good way of addressing the pending questions on role of DYRK2 in breast cancer." (PMID 33376136, 2021). "The best way forward is to generate a conditional lox-cre mouse model for DYRK2 and generate hemizygous/homozygous deletion of DYRK2 in different subtypes of breast cancer genetically engineered mouse models (GEMMs)." (PMID 33376136, 2021). "In the main study that supports the tumor-suppressor role of DYRK2 in breast cancer, the group identified DYRK2 as a priming kinase for c-Jun and c-Myc." (PMID 33376136, 2021). "This study further established the DYRK2-proteasome axis as potentially tumor promoting because higher expression of DYRK2 significantly correlated with higher mortality and poorer relapse-free survival in patients with breast cancer." (PMID 33376136, 2021). "They observed higher levels of the unphosphorylated forms after DYRK2 downregulation, followed by a shortened G1 phase and higher levels of breast cancer invasiveness." (PMID 32462403, 2020). "Conversely, using a clustered regularly interspaced short palindromic repeats (CRISPR)-based approach to generate DYRK2-knock out MDA-MB-468 breast cancer cells, DYRK2 was seen to promote breast cancer cell proliferation and tumor growth in xenografts." (PMID 32751160, 2020). "Our previous study reported the activation of mTORC1 signaling in DYRK2-knockdown human breast cancer cells." (PMID 32758357, 2020). "DYRK2 has also, in another study, been demonstrated to repress mTORC1 activation as mTORC1 activation was increased, with increased phosphorylation of S6K and 4E-BP1, in DYRK2 KD breast cancer cells." (PMID 33081032, 2020). "NOTCH1 protein levels are increased in DYRK2 knockout human breast cancer cell lines, leading to a rise of the invasion and migration potential of these cells compared to the wild type." (PMID 32462403, 2020). "Using DYRK2-depleted breast cancer cell lines, it has been described that this kinase mediates the invasion potential of these cells via CDK4 regulation." (PMID 32462403, 2020).
breast carcinoma (continued). "Dual-specificity tyrosine-regulated kinase 2 (DYRK2) controls the epithelial-to-mesenchymal transition in breast cancer and ovarian serous adenocarcinoma." (PMID 30282914, 2018). "In addition, high expression of DYRK2 led to lower survival probability in pancreatic cancer, breast cancer, and renal cancer, among others (proteinatlas.org)." (PMID 40190550, 2025). "Breast cancer tissue samples showed markedly lower DYRK2 expression than the normal tissue samples." (PMID 37886981, 2023). "DYRK2 has been reported to function as both a tumor suppressor and an oncogene in breast cancer." (PMID 37886981, 2023). "Notably, the role of DYRK2 in breast cancer has been investigated in tissue samples, cell lines, and xenograft mouse models." (PMID 37886981, 2023). "Therefore, DYRK2 expression is inversely related to the number of CSCs in breast cancer specimens and cell lines." (PMID 37886981, 2023). "However, TCGA data suggest that mRNA expression of DYRK2 is higher in breast invasive carcinoma and that higher DYRK2 expression correlates with poor survival in overall patients with breast cancer." (PMID 33376136, 2021). "Besides this, our group recently described that DYRK2 induces cell apoptosis in a NOTCH1-IC-dependent way using breast cancer cell lines." (PMID 32462403, 2020). "However, again, some discordant phenotypes have been described in vivo when studying DYRK2-depleted breast cancer cell lines." (PMID 32751160, 2020). "Moreover, the data from breast cancer tissue suggest that nuclear DYRK2 expression could promote breast cancer invasiveness and recurrence." (PMID 36622366, 2023). "Similarly, DYRK2 silencing increased the invasion, metastasis and breast cancer cell stemness." (PMID 32751160, 2020). "Likewise, higher DYRK2 expression in breast cancer and pulmonary adenocarcinoma may enhance survival." (PMID 27532268, 2016). "We observed clear expression overlap between DYRK2 and HSF1 in clustered cell populations of renal cell carcinoma and colon adenocarcinoma along with breast cancer." (PMID 36622366, 2023). "Based on single-cell RNA sequencing datasets, a clear overlap between DYRK2 and HSF1 was detected in the clustered cell populations of renal cell carcinoma, colon adenocarcinoma, breast cancer, and astrocytoma." (PMID 37886981, 2023). "DYRK2 expression is inversely related to TERT and cyclin-dependent kinase 14 (CDK14) expression in the breast cancer tissues of invasive ductal carcinoma." (PMID 37886981, 2023). "Low DYRK2 expression upregulates CD44+/CD24− and ALDH1+ CSCs in pulmonary metastases of breast cancer." (PMID 37886981, 2023). "DYRK2 expression was inversely correlated with CD44+/CD24− subpopulations and mammosphere formation in breast cancer specimens and cell lines." (PMID 37886981, 2023). "In this study, the authors used a sample size of n = 3 mice per condition and carried out an orthotopic mammary-fat-pad breast cancer xenograft comparing MCF7 control cells and stable DYRK2 knockdown cells to investigate their ability to produce tumors." (PMID 33376136, 2021). "It has also been reported that DYRK2 regulates proteotoxic resistance via HSF1, and that DYRK2 KO breast cancer cell lines show a higher apoptotic rate comparing to the wild type." (PMID 32462403, 2020). "In response to chemotherapeutic agents, DYRK2 facilitates phosphorylation-mediated degradation of neurogenic locus notch homolog protein 1 (NOTCH1), which acts as an antiproliferative mechanism in breast cancer cells." (PMID 33376136, 2021). "Therefore, this study and our study showed that KLF4 represses DYRK2 gene expression in CML, while in breast cancer, DYRK2 prevents androgen receptor-mediated activation of the KLF4 gene." (PMID 33067577, 2020). "In breast cancer, 17 genes, including RNF8, DYRK2, RB1, and TRDMT1, could be used as prognostic biomarkers of breast cancer, indicating that these genes, including RNF8, might have a strong relationship with breast cancer." (PMID 31709182, 2019).
breast carcinoma (continued). "The results showed that HIST2B, DYRK2, and RB1 might be used as predictive markers for breast cancer." (PMID 31709182, 2019). "Our results showed that HIST2H2BE, DYRK2, MBD2, and RB1 could be used as predictive markers for breast cancer." (PMID 31709182, 2019). "Besides, the knockdown of DYRK2 promoted Epithelial–mesenchymal transition (EMT) and cancer invasion in human breast cancer cells." (PMID 27532268, 2016). "Moreover, distal recurrence in patients with quadruple-negative breast cancer was shorter than that in patients with low protein expression levels of DYRK2." (PMID 37886981, 2023). "Furthermore, our results suggest that DYRK2 may be both a prognostic biomarker and a potential therapeutic target, which will be especially relevant in TN-AR-negative breast cancer patients, for whom there is no targeted therapy available." (PMID 33268814, 2021).
colorectal cancer (10 papers, 2016 to 2024). A primary or metastatic malignant neoplasm that affects the colon or rectum. "The role of DYRK2 in colorectal cancer has been investigated in tissue samples, cell lines, and xenograft mouse models." (PMID 37886981, 2023). "Microarray data from patients with colorectal cancer showed that 65.06% of tumor samples had low DYRK2 mRNA expression, whereas only 34.94% of the adjacent paracancerous tissue samples had low DYRK2 mRNA levels." (PMID 37886981, 2023). "DYRK2 expression and a combination of DYRK2 and Twist expression are predictors of liver metastasis and clinical prognosis, respectively, in patients with colorectal cancer." (PMID 37886981, 2023). "Twist, an EMT transcription factor, is inversely correlated with DYRK2 expression in colorectal cancer samples, and miR-622, a tumor-related gene, is also reported to be inversely correlated with DYRK2." (PMID 37886981, 2023). "In the same way, miR-662, miR-208a, miR-338-3p, miR-499, and miR-187-3p directly downregulate DYRK2 expression in colorectal cancer cells, fibroblasts, human intestinal cancer (HIC) cells, cardiomyocytes, and liver cancer cells, respectively." (PMID 32462403, 2020). "In addition, the DYRK2 promoter region was more highly methylated in human colorectal cancer tissues than in adjacent non-colorectal cancer tissues." (PMID 37886981, 2023). "Increased levels of DYRK2 in patients are correlated with better prognoses, improved responses to chemotherapy, and increased survival rates, particularly in instances of liver metastasis originating from colorectal cancer." (PMID 38139175, 2023). "Besides, dual-specificity tyrosine-(Y)-phosphorylation regulates kinase 2 (DYRK2) and miR-622 inhibit the invasion and migration of colorectal cancer cells by targeting the Kirsten rat sarcoma viral oncogene homolog (KRAS)." (PMID 35872695, 2022). "Similarly, recent evidence shows that DNMT1 downregulates DYRK2 gene expression methylating its promoter, thereby increasing the proliferation of human colorectal cancer cells." (PMID 32462403, 2020). "Lower expression of DYRK2 levels in liver metastases correlated with worse overall and disease-free survival, allowing for the consideration of DYRK2 as a predictive marker for liver metastases of colorectal cancer." (PMID 30282914, 2018). "Taking all, we concluded that DYRK2 a novel prognostic biomarker of human colorectal cancer." (PMID 27532268, 2016). "Thus, DYRK2/FBXW7 axis modulates Paclitaxel sensitivity in colorectal cancer cell lines." (PMID 36934104, 2023). "However, some studies have shown that miR-622 may act as a protooncogene in colorectal cancer by targeting DYRK2 and inhibiting the migration and invasion of colorectal cancer cells." (PMID 31709182, 2019). "In the case of colorectal cancer (CRC), it has been shown that DYRK2 compromises metastasis in CRC cell lines and xenografts and this also correlates with a better survival rate." (PMID 32462403, 2020). "DYRK2 expression was significantly down-regulated in colorectal cancer tissues compared with adjacent non-tumorous tissues." (PMID 27532268, 2016). "Real-time PCR by using 16 pairs of human colorectal cancer tissues showed the down-expression of DYRK2 mRNA compared with matching adjacent non-tumorous tissues (P < 0.001, paired t test)." (PMID 27532268, 2016). "In CRC, DYRK2 level was found lower in primary or metastatic CRC compared with adjacent normal colon tissues or non-metastatic CRC in all 6 colorectal carcinoma data sets respectively." (PMID 27532268, 2016). "Additionally, DYRK2 protein expression levels in colorectal cancer tissues are lower than those in adjacent non-cancerous tissues." (PMID 37886981, 2023). "In this study, we analyzed the expression of DYRK2 from Oncomine database and found that DYRK2 level is lower in primary or metastatic CRC compared to adjacent normal colon tissue or non-metastatic CRC, respectively, in 6 colorectal carcinoma data sets." (PMID 27532268, 2016).
colorectal cancer (continued). "Furthermore, DYRK2 mRNA levels were lower in metastatic and non-metastatic colorectal cancer tissues and three cell lines (HT29, SW1116, and SW480) than in non-colorectal cancer tissues and a normal human colon epithelial cell line (NCM460)." (PMID 37886981, 2023).